TBK1 (TANK binding kinase 1)
Diseases named in the same sentence as TBK1 in open-access papers (continued):
Sharing a sentence is not in itself a finding about the gene and the disease.
bladder cancer (3 papers, 2018 to 2025). "Knockdown or BX795 inhibition of TBK1 effectively controlled the proliferation and migration of bladder cancer cells by attenuating AKT phosphorylation." (PMID 40076567, 2025). "Recently, it was shown that TBK1 is upregulated in bladder cancers, and that its pharmacological inhibition dampens cell proliferation and migration." (PMID 29971063, 2018). "In bladder cancer cells and tissues, the upregulation of TBK1 expression was observed." (PMID 40076567, 2025).
Cirrhosis (3 papers, 2020 to 2025). A chronic disorder of the liver in which liver tissue becomes scarred and is partially replaced by regenerative nodules and fibrotic tissue resulting in loss of liver function. "Moreover, compared with blood EVs from the HCs, blood EVs isolated from the patients with cirrhosis exerted proinflammatory effects on macrophages, as indicated by increased p‐STING and p‐TBK1 protein levels, ISG expression, and proinflammatory factor levels." (PMID 39804962, 2025).
clear cell renal cell carcinoma (3 papers, 2022 to 2024). "More recently, TBK1 hydroxylation was identified and found to induce pVHL and phosphatase binding, which decreases its phosphorylation and enzyme activity, while the loss of pVHL hyperactivates TBK1 and promotes tumor development in clear cell renal cell carcinoma (ccRCC)." (PMID 36026437, 2022).
diffuse large B-cell lymphoma (3 papers, 2020 to 2025). "We investigated the expression and function of IKKε and TBK1, in diffuse large B‐cell lymphoma (DLBCL)." (PMID 32858764, 2020). "However, in diffuse large cell B cell lymphoma cell lines, small molecule inhibitors of TBK1/IKKε were shown to suppress survival." (PMID 40341181, 2025). "In diffuse large B-cell lymphoma (DLBCL), TBK1 mRNA levels negatively correlate with prognosis in both germinal center and non-germinal center types of DLBCL." (PMID 35395857, 2022).
head and neck squamous cell carcinoma (3 papers, 2021 to 2025). A squamous cell carcinoma that arises from any of the following anatomic sites: lip and oral cavity, nasal cavity, paranasal sinuses, pharynx, larynx, and salivary glands. "Specifically, in head and neck squamous cell carcinoma (HNSCC), the overexpression of ALKBH5 suppresses RIG‐I‐mediated IFNα secretion via the IκB kinase epsilon/TBK1/interferon regulatory factor 3 (IRF3) signaling pathway, which is closely related to tumor cell programmed cell death." (PMID 39802639, 2025).
herpesvirus infection (3 papers, 2021 to 2025). "This interaction promotes TRIM27-mediated ubiquitination of TBK1 and leads to the degradation of TBK1 via the ubiquitin–proteasome pathway, ultimately restricting the innate immune response of microglia to neurotropic herpesvirus infections." (PMID 40285022, 2025). "Numerous studies have consistently investigated the role of TBK1 in herpes infection." (PMID 38019030, 2023). "Consequently, linc-AhRA suppresses I-IFN production through facilitating TBK1 degradation and limits the microglial innate immune response against neurotropic herpesvirus infection." (PMID 34646390, 2021).
lung squamous cell carcinoma (3 papers, 2021 to 2025). "Silencing of RFWD3 in lung squamous cell carcinoma (LUSC) H2170 cells also led to upregulation of p‐STING, p‐TBK1, p‐IRF3, and p‐STAT1." (PMID 41117130, 2025).
myelofibrosis (3 papers, 2022 to 2024). A partial or complete replacement of the bone marrow stroma by fibrous tissue. "CYT387, a drug for the treatment of myelofibrosis, can inhibit interferon and interferon-stimulated gene expression through JAK1/JAK2 (kinases mediating IFN signaling) and TBK1/IKKε (kinases mediating RLR and TLR signaling) pathways." (PMID 39738014, 2024). "On the other hand, Momelotinib, a recently approved multi-kinase inhibitor for the treatment of myelofibrosis and anemia, was used in this study at a concentration targeting IKBKE, a TBK1 paralogue." (PMID 38724853, 2024). "Interestingly, fedratinib, a selective oral JAK2 inhibitor recently approved in the United States for treatment of adult patients with myelofibrosis, which has off-target activity against the VIPs BRD4, TBK1, MARK1 and CSNK2A2, also displayed a similar proviral effect in our disease system." (PMID 36305426, 2022).
Nephropathy (3 papers, 2015 to 2025). A nonspecific term referring to disease or damage of the kidneys. "In addition, TBK1 negatively regulates immunoglobulin (Ig)A class switching by attenuating non-classical NF-κB signaling; moreover, B-cell-specific TBK1 deficiency leads to aberrant antigen-induced IgA, elevated steady-state concentrations of serum IgA, and nephropathy-like symptoms in aged mice." (PMID 40076567, 2025). "Specifically, the TBK1/IKKε node was identified as a druggable therapeutic target in kidney disease that acts as a hub linking diverse inflammatory stimuli with tubular cell death and inflammatory responses." (PMID 36386242, 2022). "Genetic deficiency in a negative regulator of the noncanonical NF-κB pathway, TBK1, causes IgA hyper-production and development of nephropathy-like symptoms in mice." (PMID 26579219, 2015).
pancreatic adenocarcinoma (3 papers, 2010 to 2022). "Due to momelotinib’s ability to target TBK1, it was studied in KRAS-mutated NSCLC in combination with the MEK 1/2 inhibitor trametinib and in pancreatic adenocarcinoma in combination with nab-paclitaxel and gemcitabine chemotherapy." (PMID 34773474, 2022). "For some of these genes putative roles in pancreatic adenocarcinoma progression have been identified, as RIOK3 and MEMO1 or in tumor angiogenesis such as TBK1." (PMID 20553613, 2010). "In addition, high levels of TBK1 expression were correlated with poorer prognosis of OS in BRCA, ESCA, kidney chromophobe (KICH), KIRP, brain lower grade glioma (LGG), LUAD, Ovarian serous cystadenocarcinoma (OV), pancreatic adenocarcinoma (PAAD), and uveal melanoma (UVM)." (PMID 33679751, 2021).
proteinopathy (3 papers, 2022 to 2025). "Together, these results link TBK1 loss-of-function to defective autophagic/lysosomal clearance and enhanced proteinopathy, supporting a model in which TBK1 insufficiency promotes neuroinflammation and impaired mitochondrial/aggregate clearance in ALS." (PMID 41302089, 2025). "Considering the apparently complementary pathomechanisms of FUS and TBK1 mutations (in particular impaired protein quality control due to TBK1 haploinsufficiency and FUS proteinopathy as a consequence of FUS mutations), this is a remarkable finding." (PMID 34518945, 2022).
small cell lung carcinoma (3 papers, 2021 to 2024). Small cell lung cancer (SCLC) is a highly aggressive malignant neoplasm, accounting for 10-15% of lung cancer cases, characterized byrapid growth, and early metastasis. "This current work is in direct contrast to previously published work demonstrating that Chk1 inhibition in small cell lung cancer cells increased TBK1 and IRF3 phosphorylation, CCL5, IFN-β and CXCL10 mRNA expression, and elevated PD-L1 expression all indicative of a type I IFN response." (PMID 35006469, 2021). "A recent study found that DNA damage response (DDR) inhibitors are sufficient to induce an anti-tumor immune response in small cell lung cancer, which is mediated by the STING-TANK binding kinase 1 (TBK1)-IFN regulatory factor 3 (IRF3) pathway." (PMID 35978045, 2022).
thyroid cancer (3 papers, 2021 to 2025). "MAZ silencing markedly inhibited migration and invasion, and TBK1 overexpression reversed the inhibitory effect of MAZ silencing on thyroid cancer cells." (PMID 36988258, 2023). "The relationship between TBK1 expression level and clinical pathological characteristics in 32 patients with thyroid cancer." (PMID 36988258, 2023). "High expression of TBK1 raised viability, proliferation, migration, and invasion of thyroid cancer cells." (PMID 36988258, 2023). "The invasion cell number in TBK1‐verexpressed thyroid cancer cells was markedly raised, whereas TBK1 silencing suppressed the invasion." (PMID 36988258, 2023). "To identify the upstream factors inducing high expression of TBK1 in thyroid cancer, we further examined and identified four potential transcription factors using PROMO, hTFtarget, and animal Transcription Factor DataBase." (PMID 36988258, 2023). "MAZ silencing inhibited tumor progress of thyroid cancer cells, whereas this inhibitory effect was reversed by TBK1 overexpression." (PMID 36988258, 2023). "In this study, TBK1 expression was upregulated and a high level of TBK1 expression was related to the poor survival rate of patients with thyroid cancer." (PMID 36988258, 2023). "The function of TBK1 on thyroid cancer cells was detected using MTT, colony formation, wound healing, and Transwell assays." (PMID 36988258, 2023). "Kaplan–Meier analysis indicated that thyroid cancer patients with high TBK1 levels showed low overall survival." (PMID 36988258, 2023). "Subsequently, the cell functions of thyroid cancer cells were evaluated after transfection with TBK1 small‐interfering RNA(siRNA) and overexpression plasmids." (PMID 36988258, 2023). "MAZ silencing markedly inhibited the proliferation and migration of thyroid cancer cells and reversed the effect of TBK1 overexpression." (PMID 36988258, 2023). "Silencing MAZ and TBK1 alone significantly inhibited the PI3K/Akt/mTOR pathway in thyroid cancer cells, whereas cotransfection with MAZ siRNA and TBK1 siRNA did not strengthen the inhibitory effect of MAZ RNA or TBK1 siRNA on the PI3K/Akt/mTOR pathway." (PMID 36988258, 2023). "The expression of TBK1 in thyroid cancer and normal control tissues was analyzed using real‐time quantitative polymerase chain reaction." (PMID 36988258, 2023). "Gene set enrichment analysis using the GEO data set GSE66783 was performed to explore the mechanism of TBK1 in thyroid cancer." (PMID 36988258, 2023). "The overall survival analysis indicated that the survival rate of thyroid cancer patients with high TBK1 expression was significantly lower than that of patients with low TBK1 expression." (PMID 36988258, 2023). "The TBK1 expression was higher in thyroid cancer cell lines than in thyroid follicular epithelial cell line Nthy‐ori 3‐1." (PMID 36988258, 2023). "In the present study, we evaluated the differential expression of TBK1 in thyroid cancer and normal tissues." (PMID 36988258, 2023). "MAZ silence reversed the effects of TBK1 overexpression on thyroid cancer progression." (PMID 36988258, 2023). "High expression of TBK1 markedly increased the viability of thyroid cancer cells." (PMID 36988258, 2023). "To investigate the effects of TBK1 in thyroid cancer, we overexpressed and knockdown TBK1." (PMID 36988258, 2023). "TBK1 promoted tumor progression of thyroid cancer cells by activating the PI3K/Akt/mTOR pathway." (PMID 36988258, 2023). "Moreover, TBK1 overexpression promoted proliferation, and invasion, whereas the opposite results were obtained in TBK1 silencing thyroid cancer cells." (PMID 36988258, 2023). "Whether TBK1 participates in thyroid cancer progression by regulating other pathways requires further investigation." (PMID 36988258, 2023). "We investigated the role of TANK‐binding kinase 1 (TBK1) in the progression of thyroid cancer." (PMID 36988258, 2023). "The xenograft assay was carried out to check on the role of TBK1 in thyroid cancer." (PMID 36988258, 2023).
thyroid cancer (continued). "Briefly, TBK1 silencing repressed xenograft tumor growth in thyroid cancer cells." (PMID 36988258, 2023). "In this study, TBK1 expression was upregulated in thyroid cancer samples." (PMID 36988258, 2023). "Furthermore, the progression of thyroid cancer cells was markedly enhanced by TBK1 overexpression and inhibited by TBK1 silencing." (PMID 36988258, 2023). "Additionally, analysis of the GEO data set GSE27155 also confirmed that TBK1 was significantly upregulated in thyroid carcinoma compared with that in thyroid adenoma." (PMID 36988258, 2023). "However, current research lacks the effect of TBK1 on the apoptosis of thyroid cancer cells." (PMID 36988258, 2023). "In addition, we explored the signaling pathways regulated by TBK1 in thyroid cancer." (PMID 36988258, 2023). "High levels of TBK1 significantly raised the wound healing rate of TPC‐1 and CAL‐62 cells, whereas TBK1 silencing decreased the wound healing rate of thyroid cancer cells." (PMID 36988258, 2023). "However, whether TBK1 participates in thyroid cancer progression remains indistinct." (PMID 36988258, 2023). "Myc‐associated zinc finger protein (MAZ) silence significantly inhibited cell viability, proliferation, migration, and invasion of thyroid cancer cells, whereas the inhibitory effect was reversed by TANK‐binding kinase 1 (TBK1) overexpression." (PMID 36988258, 2023). "Cotransfection with MAZ small‐interfering RNA(siRNA) and TBK1 siRNA did not strengthen the inhibitory effect of TBK1 silencing on the thyroid cancer cells." (PMID 36988258, 2023). "Both MAZ and TBK1 silencing significantly decreased the viability and proliferation of thyroid cancer cells, whereas the inhibitory effect was not further enhanced by the cotransfection with MAZ siRNA and TBK1 siRNA." (PMID 36988258, 2023).
viral encephalitis (3 papers, 2023 to 2026). Encephalitis resulting from viral infection. "Furthermore, mutations in certain genes, e.g., TLR3 and TBK1, increase the risk of viral encephalitis." (PMID 39203963, 2024). "Nevertheless, both IDX and MRT significantly increased the viral load in brain homogenates at day 5, suggesting that TBK1/IKKε systemic inhibition could increase viral encephalitis, which is a caveat of this specific SARS-CoV-2 mouse model." (PMID 37723181, 2023).
viral pneumonia (3 papers, 2021 to 2025). Inflammation of the lung parenchyma that is caused by a viral infection. "We describe here a case of AR TBK1 deficiency in a child with recurrent vesicular skin eruptions likely triggered by herpes virus infection, recurrent viral pneumonia, who ultimately died from encephalomyelitis with a presumably viral origin." (PMID 41608123, 2025). "We describe here a Turkish boy, born to consanguineous parents and homozygous for a loss-of-function mutation of TBK1, who had experienced recurrent vesicular skin eruptions presumably triggered by herpesviral infection and five episodes of viral pneumonia since the age of 2 mo." (PMID 41608123, 2025). "It showed that NDR1 positively regulates IL-17 signaling pathway and can treat IL-17 signaling pathway-related viral pneumonia by regulating ERK1/2, p38, NF-κB, and TBK1 signaling molecules." (PMID 34699306, 2021).
allergic asthma (2 papers, 2019 to 2025). A asthma with a basis in a pathological type I hypersensitivity reaction. "Thus, cGAMP functions as a type 2 adjuvant in the lung and can promote allergic asthma in manners that dependent on the intracellular STING/TBK1/IRF3/7 signaling pathway and the resultant intercellular signaling pathway via IL-33 and ST2 might be a novel therapeutic target for allergic asthma." (PMID 31616416, 2019). "STING/TBK1/IRF3 axis and IL-33 signaling, required for cGAMP-induced allergic inflammation, may be novel therapeutic targets for allergic asthma." (PMID 31616416, 2019).
breast invasive carcinoma (2 papers, 2021 to 2024). "Specifically, DDX58, C6orf150, IKBKE, TBK1, and IRF3 exhibited a pronounced increase in breast invasive carcinoma (BRCA), while MAVS and TMEM173 expression was significantly lower in BRCA compared to normal controls." (PMID 38817870, 2024).
Cerebellar atrophy (2 papers, 2019 to 2024). Cerebellar atrophy is defined as a cerebellum with initially normal structures, in a posterior fossa with normal size, which displays enlarged fissures (interfolial spaces) in comparison to the foliae secondary to loss of tissue. "Clinical research demonstrated mesencephalic and cerebellar atrophy in patients with a p.Glu643del Tbk1 mutation." (PMID 31039129, 2019). "For example, overactivation of TBK1 by Kv3.3G592R results in a loss of Hax-1 binding to the channel, ultimately leading to increased rates of cell death, which may acting the cerebellar atrophy." (PMID 39416683, 2024). "In contrast, the Kv3.3E675K variant described here does not interfere with the TBK1 regulation and the patient does not show a cerebellar atrophy." (PMID 39416683, 2024).
Chlamydia infection (2 papers, 2010 to 2015). "Data from these experiments, in which we used BX-795 as a known inhibitor of PDK1, TBK1, and IKKε, showed significant reductions in early synthesis of IFN-β during Chlamydia infection." (PMID 25798928, 2015).
cognitive decline (2 papers, 2019 to 2025). "These cases include individuals with varying clinical characteristics, such as advanced disease stages in PSP cases, older age or cognitive decline in AD cases, and pathogenic mutations (e.g., TBK1, MAPT) in FTD cases." (PMID 39976789, 2025).
depression (2 papers, 2019 to 2024). "While the link inflammation-TBK1 activation has not been identified in major depressive disorders, a consistent hypothesis is that an inflammatory profile modulates neuronal function to behavioural arousal." (PMID 30866491, 2019).
diabetic neuropathy (2 papers, 2024 to 2025). A chronic, pathological complication associated with diabetes mellitus, where nerve damages are incurred due to diabetic microvascular injury involving small blood vessels that supply these nerves, resulting in peripheral and/or autonomic nerve dysfunction. "For instance, TBK1 has been shown to alleviate diabetic neuropathy by inhibiting microglial pyroptosis." (PMID 40552323, 2025).
diabetic retinopathy (2 papers, 2022 to 2025). "Interestingly, we also detected an increased expression of TBK1 in diabetic retinopathy samples, which suggested an association between TBK1 and the disease." (PMID 36307391, 2022).
E. coli infection (2 papers, 2024 to 2025). "WB analysis demonstrated that E. coli infection markedly upregulated the expression of cGAS and Bax/Bcl2, along with the cleavage of caspase 3 and phosphorylation levels of STING, TBK1, IκBα, and P65." (PMID 41302013, 2025). "Different from E. coli infection, S. aureus infection induced IRF7 and phosphorylation of IRF7 through activating TRAF3‐IKKε/TBK1 axis, bypassing MyD88." (PMID 39166412, 2024).